TNF (tumor necrosis factor)
Diseases named in the same sentence as TNF in open-access papers (continued):
Sharing a sentence is not in itself a finding about the gene and the disease.
inflammatory myopathies (continued). "Inhibition of TLR4 and HMGB1 signaling significantly reduced the expression of TNF-α and IL-6 cytokines in a myopathy mouse model, suggesting that the HMGB1/TLR4 axis may involve in skeletal muscle atrophy." (PMID 36497194, 2022). "Furthermore, upregulation of Nogo-A in dystrophin-deficient (mdx) murine model, myopathy and Duchenne muscle dystrophy (DMD) clinical biopsies was associated with upregulation of CHOP, IL-6 and TNF-α." (PMID 33572505, 2021). "Therefore, it is expected that DPHC isolated from IO would be developed as a TNF-α inhibitor against inflammatory myopathy." (PMID 33114618, 2020). "The results in preliminary studies on inflammatory myopathies suggest that TNF blocking might be useful, but it is also emphasized that further studies are needed in order to clarify if this type of treatment is indeed useful." (PMID 22505941, 2012). "We hypothesized IL-6 and TNF-α may be involved in ET-1–induced inflammatory myopathy." (PMID 35468098, 2022). "However, in mice with a genetic defect similar to dystrophy and myopathy, subcutaneous injections of TNF-blocker etanercept impeded inflammatory and degenerative histological changes, and low-dose infliximab was beneficial for muscle strength and muscle fibrosis." (PMID 27672678, 2016). "Finally, as we did not detect anti-inflammatory effects of β-agonists in C2C12 skeletal muscle cells, but instead potentiation of TNF-α action, we suggest caution in the proposed use of β-agonists as therapeutic agents for inflammatory myopathies and urge for further study." (PMID 24603712, 2014). "Nevertheless, it has previously been shown that TNF-alpha can be expressed not only in inflammatory cells but also in injured muscle fibers and fibroblasts in response to muscle injury (crush-injury) as well as in muscle fibers and cells in the connective tissue in inflammatory myopathies." (PMID 22505941, 2012). "In this study, we define the specific transcriptomic features of GM, revealing a distinct activation of the IFNγ pathway compared to other myopathies, as well as an increase in multiple proinflammatory cytokines, including IL1B, TNF, and TGFB1." (PMID 40568658, 2025). "A previous study showed that IO downregulated pro-inflammatory cytokines and muscle atrophy proteins against TNF-α, thereby demonstrating its potential as a TNF-α inhibitor for inflammatory myopathy." (PMID 35621931, 2022). "Muscle biopsies from myopathy and DMD patients had significant increases in Nogo-A, CHOP, IL-6, and TNF-α expression at both the mRNA and protein levels." (PMID 33572505, 2021). "Matching our results from glucocorticoid-treated TNF-tg mice, 11β-HSD1 deletion also mitigated myopathy in wild-type animals receiving excess exogenous glucocorticoid." (PMID 34360594, 2021). "While CXCL10 is predominantly associated with a Th1 response, it has been recently identified in inflammatory myopathies, and secretion of CXCL10 from human fetal skeletal muscle cells is induced by treatment with either interferon (IFN)-γ or TNFα." (PMID 26856410, 2016). "TNF-α and IFN-γ are commonly expressed in the skeletal muscle of patients suffering from inflammatory myopathies, in which CD8+ T cells infiltrate and play a critical role in disease progression." (PMID 26417430, 2015). "Several tumor necrosis factor (TNF) superfamily genes (TNFSF8, LTB, TNFSF12, TNFSF13B, TNFSF14, TNFSF13, EDA) were upregulated, with LTB and EDA reaching higher levels than in other inflammatory myopathies." (PMID 41441888, 2025). "Finally, we found that myopathy and DMD patients group (n=10) had significantly elevated levels of Nogo-A, CHOP, IL-6, and TNF-α mRNA compared with healthy subjects group (n=5)." (PMID 33572505, 2021).
inflammatory myopathies (continued). "However, aside from directly accessing the myocytes, this virus can induce myopathy, muscle weakness and atrophy indirectly by upregulating proinflammatory cytokines, such as interleukin 1 beta (IL-1β) and 6 (IL-6), C-reactive protein (CRP), and tumor necrosis factor (TNF)." (PMID 34248502, 2021). "mRNA-expression of APP, NCAM, iNOS, TNF-α and TGF-β was higher in GNE myopathy compared to controls, yet this was not statistically significant." (PMID 23496965, 2013).
brain diseases (39 papers, 2008 to 2025). "TNF-α is a proinflammatory cytokine that is associated with impaired brain function and numerous brain disorders." (PMID 37771706, 2023). "Previous implications have shown that the alterations of the levels of TNF-α in the serum and/or in the cerebrospinal fluid are associated with various brain diseases in human." (PMID 30072733, 2018). "In the context of brain disease or injury, such as SE, inflammatory factors interferon gamma or tumor necrosis factor alpha activate microglia and increase their proliferation in response to damage." (PMID 41300233, 2025). "IDO1 plays a critical pathogenic role in brain disorders when activated by proinflammatory cytokines, such as interferon γ (IFN-γ), interleukin-6 (IL-6), and tumor necrosis factor α (TNF-α)." (PMID 37191427, 2023). "Following activation, Mincle and its downstream syk increase inflammatory cytokine production, such as TNF-α and IL-6, by regulating the NFκB signal in brain diseases." (PMID 37189208, 2023). "In contrast, the ability of Q3G-RF to restore the DDVP-induced elevation of NO and TNF-α confirms that it can serve as a potential anti-inflammatory agent in brain diseases mediated by inflammation." (PMID 36006156, 2022). "TNF-α is a crucial stimulator of necroptosis via TNF-α/TNFR1/RIPK1/RIPK3/MLKL pathway in several brain diseases." (PMID 33724154, 2021). "Few studies have used the intrathecal/intraventricular route to deliver an anti-TNF-α drug for treating brain disease." (PMID 27445694, 2016). "Few studies have used the intrathecal/intraventricular route to deliver anti-TNF-α drugs to treat brain disease." (PMID 27445694, 2016). "Systemic administration of anti-TNF-α therapy attenuates increased brain levels of TNF-α in brain disorders." (PMID 27445694, 2016). "Therefore, MCs and microglia in the CNS are a source of pro-inflammatory cytokines, including TNF and IL-33, that mediate many brain diseases." (PMID 38542222, 2024). "Clark IA, Vissel B. Inflammation-sleep interface in brain disease: TNF, insulin, orexin." (PMID 34161418, 2021). "Modulation of RLIP76 by TNF-α might be relevant to the treatment outcome of brain disorders and tumors wherein the blood-brain barrier is inflamed, as it may alter drug transport across the barrier." (PMID 26406496, 2015). "While normal physiological levels of IL-6 and TNF-α protect neurons and glia against glutamate-induced toxicity, elevated levels and toxicity can arise under conditions of hypoxia and brain damage, and are seen in a number of brain disorders." (PMID 20509936, 2010). "In addition, studies have shown that moderate physical exercise could reduce the levels of IL-1β and TNF-α in the hippocampus or serum in interventions for brain disorders, although the effect on IL-6 is subject to specific discussion." (PMID 36212646, 2022). "The release of inflammatory cytokines such as interleukin (IL)-1, IL-6, IL-17 and tumor necrosis factor alpha (TNF-α) which have been incriminated as being part of pathological signal cascades in brain diseases could have been released in these animals, although these cytokines were not measured." (PMID 28686693, 2017). "Previous studies have demonstrated that peripheral TNF plays an important role in the pathogenesis of SAE and is involved in the disruption of the BBB in many brain diseases." (PMID 30837977, 2019). "Although there are very few data about how LPS regulate TNF-α in the brain, LPS-regulated TNF-α via NF-κB in brain microglia has been shown in some brain disorders." (PMID 29484107, 2018). "When analyzing the datasets from the brain diseases for the observed disruption of the BBB, we focused on endothelial cell population #22, which showed high responsiveness to TNFα and IFN-γ signaling, and decrease of tight junction-related genes, and increase of death-related genes." (PMID 40450318, 2025).
vasculopathy (37 papers, 2009 to 2025). "We showed that 3D microvessels and angiogenic factor-induced sprouts exposed to key pro-inflammatory and pro-fibrotic cytokines (TNFα and TGFβ) undergo structural alterations consisting of destructive vasculopathy (loss of small vessels)." (PMID 36209279, 2022). "We show that 3D microvessels and angiogenic factor-induced sprouts exposed to key pro-inflammatory and pro-fibrotic cytokines (TNFα and TGFβ) undergo structural alterations typical of destructive vasculopathy (loss of small vessels)." (PMID 36209279, 2022). "Endothelin 1 (ET-1; at pixel density 11427 ± 2065.46), a molecule that has been implicated in the development and progression of vascular disorders and usually secreted by endothelial cells upon stimulation by proinflammatory cytokines or hypoxia, could also be detected upon TNFα treatment." (PMID 24195074, 2013). "The cause of central nervous system inflammation and vasculopathy caused by NB may be the invasion of the central nervous system by Brucella, which interacts with astrocytes and microglia and induces the secretion of TNF-α, IL-1β and IL-6 by astrocytes and microglia." (PMID 38730327, 2024). "The amount and activity of the TNF-α secreted by HMECs stimulated with KTx-IgG from patients with vasculopathy was sufficient to induce subsequent THP-1 monocytic cell activation." (PMID 37965310, 2023). "Currently, a tailored treatment with anti-TNFα agents shows a crucial role in treating patients with a vasculopathy phenotype." (PMID 37179309, 2023). "The correlation between RAB-levels and TNF-α in (kidney) allograft vasculopathy patients should be confirmed in larger clinical studies and potentially serve as valuable, non-invasive biomarkers for monitoring graft health and failure risk." (PMID 37965310, 2023). "To induce a diseased in vitro state relevant to SSc and other vasculopathies, we assessed the stability of the established sprouts upon exposure to key pro-inflammatory (TNFα) and pro-fibrotic (TGFß) cytokines." (PMID 36209279, 2022). "At present, the mainstay of treatment of vasculopathy and autoinflammation phenotypes consists of anti-TNF-agents (etanercept, infliximab, adalimumab) with impressive reductions in stroke incidence." (PMID 35911698, 2022). "Anti-TNF agents are the mainstay of treatment of vasculopathy and autoinflammation phenotypes and it is recommended that patients already on these agents, who show some response, continue therapy until conditioning for HCT starts, even until engraftment." (PMID 35911698, 2022). "Anti-TNF agents, etanercept in particular, are the mainstay of treatment for the inflammatory and vasculopathy phenotypes." (PMID 34324127, 2021). "TNF-α is a potent activator of NF-κB and is involved in the pathogenesis of various vascular disorders by impairing the NO/sGC/cGMP pathway." (PMID 30765689, 2019). "In addition, protein expression of inducible NOS and tumor necrosis factor alpha (TNFα) in aortas was increased, as were plasma levels of chemerin, which has been proposed as a possible link among metabolic and vascular disorders and inflammation." (PMID 40559470, 2025). "TNFα has been evaluated as key cytokine in the onset of the vasculopathy manifestations." (PMID 37179309, 2023). "Interestingly, we found that KTx-IgG from patients with vasculopathy increased the TNF-a response of HMECs to their natural activator thrombin and PMA." (PMID 37965310, 2023). "Thus, systemic and local cytokine productions could be initiated and damage the CNS together with possible vasculopathy in the brain, as researchers have reported elevation of tumor necrosis factor-α, interleukin-6 (IL-6), and IL-10 in CSF in SLE patients." (PMID 29449817, 2018). "Tumor necrosis factor (TNF-α) blockade is the treatment of choice for the vasculopathy, but often fails to reverse refractory cytopenia." (PMID 34324127, 2021).
vasculopathy (continued). "Anti-TNF therapy achieved 100% clinical/radiological stabilization by suppressing thromboinflammatory cascades, yet failed to reverse established atrophy—a dissociation highlighting TNF-α's role in acute vasculopathy but not chronic neurodegeneration." (PMID 41413740, 2025). "Tumor necrosis factor α (TNFα) inhibition resolves vasculopathy, but not cytopenia." (PMID 37512494, 2023). "However, anti-TNF agents do not cure the hematological phenotype and in a proportion of patients, vasculopathy persists despite anti-TNF treatment." (PMID 34324127, 2021). "In conclusion, exposure of HMECs to KTx-IgG from patients with allograft vasculopathy, but not KTx-IgG from patients without vasculopathy or healthy Con-IgG, triggers signaling through the PAR1-AP-1/c-FOS-miRNA-let7-axis, to control TNF-α gene transcription and TNF-α-induced monocyte activation." (PMID 37965310, 2023).
gastrointestinal disease (27 papers, 2011 to 2025). A disease that occurs in the gastrointestinal system, excluding the hepatobiliary system. "TNF-α is crucial in the regulation of gastrointestinal diseases, with its expression in intestinal cells closely associated with intestinal barrier impairment." (PMID 39310259, 2024). "The effects of tumor necrosis factor (TNF), a cytokine with a central pathogenic role in several gastrointestinal diseases, on barrier integrity are the most thoroughly investigated." (PMID 37402104, 2023). "Recent studies using rat models of gastrointestinal disease have found that taVNS upregulates intestinal ACh and α7nAChR expression, while simultaneously reducing the levels of inflammatory cytokines such as TNF-α, IL-1β, and IL-6." (PMID 40564012, 2025). "Still, TNF-α, often increased during gastrointestinal diseases, statistically decreased from D0 to D24 in dogs supplemented with yeast probiotic S. cerevisiae." (PMID 39981313, 2025). "Biologic agents targeting TNF-α are currently in clinical use for immune-mediated inflammatory rheumatological and gastrointestinal disease." (PMID 36980727, 2023). "Lastly, biologic agents targeting TNF-α are currently in clinical use for immune-mediated inflammatory rheumatological and gastrointestinal diseases." (PMID 36980727, 2023). "We know that alterations of cytokines like interleukin-1 (IL-1), IL-6, and tumor necrosis factor-alpha (TNF-alpha) are known manifestations in various gastrointestinal diseases, including CRC." (PMID 34523041, 2022). "Collectively these findings provide further functional evidence of a contribution by TNFα to the production of visceral pain in gastrointestinal disease and highlight the role of TNFR1‐mediated p38 MAPK signalling to the pro‐nociceptive activity of TNFα." (PMID 35775903, 2022). "Our findings demonstrate a contribution of TNFR1, p38 MAPK and TRPV1 to TNFα‐induced sensitization of colonic afferents, highlighting the potential utility of these drug targets for the treatment of visceral pain in gastrointestinal disease." (PMID 35775903, 2022). "As the use of anti–TNF-α treatment rises, due to increasing indications of rheumatologic and gastrointestinal diseases, mycobacterial disease will likely become more common." (PMID 21392437, 2011). "MIME has also been successfully used to predict the response of IBD patients to a low FODMAP diet or anti-TNF treatment, the efficacy of synbiotic treatment of gastrointestinal disease in children, or the prediction of the clinical outcome of bariatric surgery." (PMID 37085526, 2023). "TNFα has been linked to the production of abdominal pain in gastrointestinal disease due to its enhanced expression in disease states such as IBS and IBD, combined with data showing TNFα‐mediated visceral nociceptor sensitization and TNFR1 expression in colonic nociceptors." (PMID 35775903, 2022). "Although our findings are promising, a further validation of Tregs as a potential biomarker for TNF responsiveness is necessary in an independent cohort of AS and other rheumatic and gastrointestinal diseases where anti-TNF blockers are successfully administered." (PMID 32560733, 2020). "Although our findings are promising, a further validation of CD8-positive NK cells as a potential biomarker for TNF responsiveness is necessary in an independent cohort of AS and other rheumatic and gastrointestinal diseases where anti-TNF blockers are successfully administered." (PMID 30157966, 2018). "Pro-inflammatory cytokines such as TNF-α, IFN-γ, and IL-1 are biomarkers of gastrointestinal diseases." (PMID 37299439, 2023). "The inflammatory mediators that cause joint inflammation, including the proinflammatory cytokines interleukin (IL)-1β, IL-6, and tumor necrosis factor (TNF)-α, may spread systemically, leading to comorbid disease, including cardiovascular, pulmonary, kidney, and gastrointestinal disease." (PMID 35330475, 2022).
gastrointestinal disease (continued). "In the same study, no patients with previous gastrointestinal disease flared upon exposure to ICIs: however, one patient in our study with inactive IBD started prophylactic treatment with a TNF-α inhibitor upon initiation of ICIs." (PMID 34208218, 2021).
colon (22 papers, 2009 to 2024). "Several signaling pathways, such as Fas/FasL, TNFα/TNF receptor, TRAIL/TRAIL-R, and EGF/EGFR, have been suggested as therapeutic targets to induce apoptosis in gastrointestinal tract cancers." (PMID 19742123, 2009).
gastrointestinal disorders (22 papers, 2013 to 2025). "Pro-inflammatory cytokines such as IFN-γ, TNF-α, IL-1, and IL-6 are measured as biomarkers for gastrointestinal disorders, including ETEC-infection diarrhea." (PMID 35747266, 2022). "Among these two anti‐TNF agents, adalimumab may have fewer adverse effects (odds ratio [OR] 0.62 [95% confidence intervals [CI] 0.42–0.91]), mostly related to infections, musculoskeletal disorders, and gastrointestinal disorders." (PMID 40772520, 2025). "Moreover, we verified whether the expression levels of hsa‐let7‐5p was correlated with any inflammatory markers, such as IL‐6, TNF‐α, fibrinogen, and D‐dimer and with specific diseases symptoms, such as fever, dry cough, dyspnea, and gastrointestinal disorders." (PMID 36073344, 2022). "None of the patients in our cohort who had resumed anti-TNFα for digestive disease had IRIS after restarting treatment." (PMID 38957691, 2024).
connective tissue diseases (19 papers, 2005 to 2025). "Ten patients were ruled out due to improper diagnosis of lupus syndrome, due to pre-existing lupus syndrome or due to mixed connective tissue disease before introduction of anti-TNF alpha therapies." (PMID 15899041, 2005). "Clinically, MAb to TNF-α downregulate inflammation in connective tissue diseases." (PMID 40971988, 2025). "TNF signalling pathway plays an important role in a variety of connective tissue diseases." (PMID 35132912, 2022). "Studying the impact of pro-inflammatory cytokines like tumor necrosis factor-alpha (TNF-α) and interleukin-6 (IL-6) on placental dysfunction and FGR in patients with connective tissue disorders could lead to targeted interventions." (PMID 38993471, 2024). "Elevated tumor necrosis factor (TNF)-alpha and interleukin 6, and multiple serum antibodies were detected, but no connective tissue disease could be diagnosed." (PMID 39478870, 2024).